RNU6-885P (RNA, U6 small nuclear 885, pseudogene)
Gene: Small nuclear RNA gene on chromosome 10 (42,832,447 to 42,832,550, reverse strand). Ensembl gene ENSG00000252416.
Homologues: Orthologues: chimpanzee U6 (99% identical), macaque U6 (95% identical), macaque U6 (94% identical), macaque U6 (92% identical), mouse Gm55671 (55% identical). Paralogues in human: RNU6-745P (79% identical), RNU6-1011P (78% identical), RNU6-558P (77% identical), RNU6-1270P (76% identical), RNU6-26P (76% identical), RNU6-774P (76% identical), RNU6-1158P (75% identical), RNU6-1273P (75% identical), RNU6-189P (75% identical), RNU6-727P (75% identical), RNU6-767P (75% identical), RNU6-946P (75% identical), and 1285 more.